ZBED10P (zinc finger BED-type containing 10, pseudogene)
Synonyms: formerly C7orf29; ZBED6CL
Gene: Transcribed unitary pseudogene on chromosome 7 (150,329,871 to 150,331,115, forward strand). Ensembl gene ENSG00000188707.
Genetic constraint (gnomAD): Loss-of-function variants: 4 observed, 6.7 expected, observed/expected ratio (o/e) 0.6, 90% interval 0.29 to 1.35. That is too few expected variants to judge how well the gene tolerates losing a copy. Missense variants: 154 observed, 152.48 expected, observed/expected ratio (o/e) 1.01, 90% interval 0.88 to 1.15. Synonymous variants: 74 observed, 66.34 expected, observed/expected ratio (o/e) 1.12, 90% interval 0.92 to 1.35.